RNA5SP68 (RNA, 5S ribosomal pseudogene 68)
Synonyms: RN5S68
Gene: Ribosomal RNA pseudogene on chromosome 1 (173,969,318 to 173,969,436, reverse strand). Ensembl gene ENSG00000200755.
Diseases named in the same sentence as RNA5SP68 in open-access papers:
RNA5SP68 is named in the same sentence as 2 diseases in open-access papers, as found by Europe PMC text mining. Sharing a sentence is not in itself a finding about the gene and the disease.
RNA5SP68 shares sentences with these, for which no sentence is quoted: cancer (1 paper); tumour (1).